DMD (dystrophin)
Diseases named in the same sentence as DMD in open-access papers (continued):
Sharing a sentence is not in itself a finding about the gene and the disease.
Duchenne muscular dystrophy (continued). "Children with Duchenne Muscular Dystrophy (DMD) have dystrophin-deficient muscles, making them susceptible to contraction-induced muscle injury, which triggers the immune system and exacerbates muscle damage." (PMID 38983605, 2024). "As a proof of principle, we induced genetic deficiencies for DMD (Duchenne muscular dystrophy, OMIM#310200) and CAPN3 (limb-girdle muscular dystrophy type 2A (LGMD2A), OMIM#253600) in healthy hiPSC-based 3D-TESMs." (PMID 38389096, 2024). "Its activity protects against impairment of cardiac contractility resulting from dystrophin deficiency in Duchenne muscular dystrophy, whereas loss of function destabilizes muscle adhesion and force generation." (PMID 39572783, 2024). "Duchenne muscular dystrophy is caused by a mutation in the largest gene in the human genome, DMD, which contains 79 exons." (PMID 39023735, 2024). "In patients with Duchenne muscular dystrophy, the X-linked mutation can interfere with the ability to produce functional dystrophin in the muscles." (PMID 39201459, 2024). "Precision medicine has also developed a method for correcting a frameshift mutation in the dystrophin gene in Duchenne muscular dystrophy (DMD) patients." (PMID 38355681, 2024). "Duchenne muscular dystrophy (DMD) is a rare, X-linked neuromuscular disease caused by mutations in the DMD gene resulting in progressive muscle degeneration, loss of independent ambulation, and life-threatening cardiac and respiratory complications." (PMID 39342355, 2024). "Duchenne muscular dystrophy (DMD) is a fatal muscle wasting disease caused by mutations in the dystrophin gene." (PMID 39649621, 2024). "Duchenne muscular dystrophy is caused by mutations in the Dmd gene, which encodes dystrophin protein." (PMID 38280977, 2024). "Examples include granulomatous disease (OMIM 306400) due to CYBB mutation, Duchenne muscular dystrophy (OMIM 310200) due to DMD mutation, and McLeod syndrome (OMIM 300842) due to XK mutation." (PMID 39000307, 2024). "Duchenne muscular dystrophy (DMD) is an incurable X‐linked recessive genetic disease caused by mutations in the dystrophin gene." (PMID 38188603, 2024). "Duchenne muscular dystrophy (DMD) is an X-linked recessive disease characterized by mutations in the dystrophin gene, causing motor and pulmonary function decline." (PMID 39379403, 2024). "Patients with mutations in Dystrophin develop Duchenne Muscular Dystrophy (DMD), and frequently exhibit cognitive impairments in the absence of brain malformations, suggesting a general role for the DGC in synapse development and function." (PMID 38179984, 2024). "It was approved by the Food and Drug Administration (FDA) in February 2021 to treat Duchenne muscular dystrophy (DMD) in patients whose DMD gene mutation is amenable to exon 45 skipping." (PMID 38672266, 2024). "In the MLPA-negative DMD group, we found three pathogenic variants in the DMD gene (c.7354G>T, c.7993A>G, and c.5190G>C) that have been described in patients with Duchenne muscular dystrophy." (PMID 38818036, 2024). "Duchenne Muscular Dystrophy (DMD) is caused by different mutations of the dystrophin gene, located on the X chromosome." (PMID 38438561, 2024). "Duchenne muscular dystrophy, Becker muscular dystrophy, and X-linked dilated cardiomyopathy are caused by the loss of dystrophin at the muscle cell surface and a concomitant loss of the entire DGC, including SSPN." (PMID 38892308, 2024). "Becker muscular dystrophy (BMD), is an X-linked neuromuscular disease caused by dystrophin gene mutation which results in a partial defect of dystrophin, whereas a complete loss of the protein causes the Duchenne muscular dystrophy(DMD)." (PMID 39044225, 2024). "Duchenne Muscular Dystrophy (DMD) is a debilitating disease characterized by progressive muscle wasting due to X-linked recessive mutations in the dystrophin (DMD) gene." (PMID 39669499, 2024).
Duchenne muscular dystrophy (continued). "Duchenne muscular dystrophy (DMD) is a severe X-linked genetic disorder caused by an array of mutations in the dystrophin gene, with the most commonly mutated regions being exons 48–55." (PMID 39796016, 2024). "It has been reported that autophagic activity is disturbed in the skeletal muscles of dystrophin-deficient mdx mice and patients with Duchenne muscular dystrophy (DMD)." (PMID 38228650, 2024). "Duchenne muscular dystrophy (DMD) is an X-linked disorder that results from mutations in the dystrophin gene; it is characterized by fibrofatty replacement of skeletal and cardiac muscle." (PMID 39664666, 2024). "Duchenne muscular dystrophy (DMD) is a hereditary muscle disease caused by mutations in the DMD gene on the X chromosome." (PMID 38724973, 2024). "The Duchenne muscular dystrophy (DMD) syndrome is caused by mutations within the large DMD gene located on the X chromosome (Xp21)." (PMID 38802640, 2024). "Duchenne Muscular Dystrophy (DMD) is a devastating X-linked genetic disorder characterized by progressive muscle degeneration due to mutations in the dystrophin gene." (PMID 38983605, 2024). "Duchenne muscular dystrophy (DMD) is caused by mutations in the gene encoding dystrophin, a subsarcolemmal protein whose absence results in increased susceptibility of the muscle fiber membrane to contraction-induced injury." (PMID 39717824, 2024). "Duchenne muscular dystrophy (DMD) affecting 1 in 3500–5000 live male newborns is the frequently fatal genetic disease resulted from various mutations in DMD gene encoding dystrophin protein." (PMID 39009678, 2024). "In the murine model of the Duchenne muscular dystrophy (the dystrophin/utrophin-deficient mouse) large clusters of nestin+ striated cells co-expressing cardiac troponin I, desmin and connexin 43, were present in the hearts near the end stage of the disease." (PMID 36690826, 2024). "Expression of micro-dystrophin, a potential novel gene therapy product for Duchenne muscular dystrophy, in 3D-TESMs partially rescued the dystrophic phenotype caused by DMD knock down." (PMID 38389096, 2024). "Duchenne muscular dystrophy (DMD) is an X-linked multifactorial handicap caused by mutations in the dystrophin (or DMD) gene." (PMID 38667332, 2024). "Duchenne Muscular Dystrophy, the most prevalent form of Muscular Dystrophy, is due to the loss of functional Dystrophin." (PMID 38812789, 2024). "Duchenne muscular dystrophy (DMD) is a disease caused by nonsense mutations resulting from deletions, duplications or point mutations in the DMD gene." (PMID 37847216, 2024). "Duchenne muscular dystrophy (DMD) is an X-linked recessive disorder caused by a truncated dystrophin (DMD) gene, frequently due to mutations of inherited or random translocations between chromosome 21 and the X chromosome." (PMID 38731986, 2024). "Duchenne Muscular Dystrophy (DMD) is caused by mutations in the dystrophin gene, leading to increased muscle fiber fragility, loss of satellite cell polarity, and functional impairment, which compromise muscle regeneration." (PMID 39595972, 2024). "Duchenne muscular dystrophy is a devastating disease that results from mutations in the dystrophin gene (DMD) and can lead to heart and respiratory failure." (PMID 36979114, 2023). "Duchenne muscular dystrophy (DMD) is an inherited muscular disorder caused by mutations in the dystrophin gene." (PMID 36831159, 2023). "The potential of prime editing has been tried on two muscular diseases: Duchenne muscular dystrophy, caused by a mutation in the DMD gene, and spinal muscular atrophy, caused by a mutation in the SMN2 gene." (PMID 36831203, 2023). "The most fatal form of muscular dystrophy is Duchenne muscular dystrophy which occurs due to aberration in the DMD gene-encoding muscular dystrophin protein." (PMID 37856057, 2023). "Duchenne muscular dystrophy (DMD) is a muscular disorder caused by mutations in the dystrophin gene on the X chromosome." (PMID 36833410, 2023).
Duchenne muscular dystrophy (continued). "For example, Duchenne muscular dystrophy (DMD) is a progressive muscle wasting disease resulting from loss of the dystrophin gene that results in muscle sarcolemma stiffness and susceptibility to damage and muscle degeneration." (PMID 40757564, 2023). "Duchenne muscular dystrophy (DMD) is an autosomal recessive myophathy caused by mutations in the dystrophin gene." (PMID 38044945, 2023). "While loss of the full-length dystrophin results in Duchenne muscular dystrophy, mutations additionally disrupting other isoforms result in exacerbated phenotypes." (PMID 36900171, 2023). "AMONDYS 45 (casimersen) is an antisense oligonucleotide therapy used to treat Duchenne muscular dystrophy (DMD), a rare genetic disorder characterized by a mutation in the DMD gene." (PMID 38283433, 2023). "For example, there are more than 7000 known mutations in dystrophin that result in Duchenne muscular dystrophy (DMD)." (PMID 37892218, 2023). "Duchenne muscular dystrophy (DMD) is a rare neuromuscular disease caused by pathogenic variations in the DMD gene." (PMID 36982290, 2023). "We studied the DE50-MD canine model of Duchenne muscular dystrophy, which is deficient in full length brain dystrophin (Dp427) isoforms and has a neurocognitive phenotype." (PMID 36932329, 2023). "utilize the dual CRISPR-Cas3 system to induce a large deletion (∼340 kb) at the dystrophin exon 45–55 region for multi-exon skipping (MES) in various Duchenne muscular dystrophy (DMD) mutation patterns." (PMID 37625413, 2023). "Duchenne muscular dystrophy (DMD) is a disease with a life-threatening trajectory resulting from mutations in the dystrophin gene, leading to degeneration of skeletal muscle and fibrosis of cardiac muscle." (PMID 37545481, 2023). "Duchenne muscular dystrophy is a rare and lethal hereditary disease responsible for progressive muscle wasting due to mutations in the DMD gene." (PMID 37305116, 2023). "Duchenne muscular dystrophy (DMD) is a hereditary muscle disorder caused by the mutation of the dystrophin gene." (PMID 37175515, 2023). "Duchenne muscular dystrophy (DMD) is an X-linked severe progressive muscle disease caused by mutations in the Dmd gene that codes for the dystrophin protein." (PMID 36265896, 2023). "The absence or deficiency of dystrophin due to mutations in the Dystrophin gene leads to spectrum of dystrophinopathies including Duchenne muscular dystrophy (DMD), Becker muscular dystrophy (BMD), and dilated cardiomyopathy (DCM) in humans and animal models." (PMID 37759719, 2023). "As an example, dystrophin-deficient mice exhibit a normal life span and mild cardiomyopathy, which is in contrast with the human phenotype of Duchenne muscular dystrophy." (PMID 36834573, 2023). "Duchenne muscular dystrophy (DMD) is an X-linked severe progressive muscle wasting disease caused by a deficiency in dystrophin protein." (PMID 37189573, 2023). "Duchenne muscular dystrophy (DMD) is a X linked disorder with mutations in the dystrophin Xp21 gene resulting in a reduction of dystrophin, a protein that is essential for the stability of the sarcolemma." (PMID 37189996, 2023). "Duchenne muscular dystrophy (DMD) is caused by the absence of the dystrophin protein and a properly functioning dystrophin-associated protein complex (DAPC) in muscle cells." (PMID 36768550, 2023). "One prominent dog study used CRISPR-Cas9 (delivered by adeno-associated viruses AAV) to restore the expression of dystrophin in a dog model of Duchenne muscular dystrophy, accompanied by improved muscle histology and amelioration of the disease." (PMID 37190012, 2023). "Mutations in the dystrophin gene result in the absence or dysfunction of dystrophin, causing Duchenne muscular dystrophy (DMD)." (PMID 38274897, 2023).
Duchenne muscular dystrophy (continued). "Gene therapy can be potentially adapted to restore dystrophin expression in Duchenne muscular dystrophy (DMD), an X-linked inherited disease caused by mutations in the gene coding for dystrophin that leads to a life-threatening muscle-wasting condition." (PMID 36986717, 2023). "Duchenne muscular dystrophy (DMD) is a lethal X-linked disease caused by mutations in the dystrophin gene, resulting in muscle degeneration, wasting, and weakness." (PMID 37999748, 2023). "Given the importance of the full-length dystrophin, whose loss is responsible for Duchenne muscular dystrophy, and the predominance of the transcript encoding Dp427m, its expression patterns were analyzed in more detail." (PMID 36900171, 2023). "Duchenne muscular dystrophy (DMD) is a lethal muscle disease caused by spontaneous mutations in the dystrophin gene, located on chromosome Xp21.2." (PMID 37270528, 2023). "Duchenne muscular dystrophy (DMD) is a severe rare neuromuscular disorder caused by mutations in the X-linked dystrophin gene." (PMID 38057384, 2023). "Alterations in the dystrophin protein, which is present in both skeletal and cardiac muscle, cause Duchenne muscular dystrophy (DMD) and can lead to DCM by the age of 20, resulting in death." (PMID 37025725, 2023). "Duchenne muscular dystrophy (DMD) is a severe muscular disorder caused by mutations in the dystrophin gene." (PMID 37240237, 2023). "Mutations that prevent the production of proteins in the DMD gene cause Duchenne muscular dystrophy." (PMID 37298068, 2023). "Mutations in the DMD (Dystrophin) gene are implicated in Duchenne’s Muscular Dystrophy, an X-linked recessive disorder." (PMID 37766271, 2023). "The efficient repair of the DMD Q1392X mutation (68.3±10.1%) is also demonstrated in a humanized mouse model of Duchenne muscular dystrophy (DMD) after AAV delivery, achieving restoration of expression for gene products." (PMID 37098587, 2023). "Duchenne muscular dystrophy (DMD) is a severe neuromuscular disorder caused by mutations in the dystrophin gene, which leads to progressive degradation of skeletal muscle structure, a loss of mobility, and, eventually, premature death." (PMID 37759703, 2023). "Patients with BMD have a wide variety of disease severity ranging from asymptomatic to as severe as Duchenne muscular dystrophy (DMD)—a disease primarily caused by out-of-frame dystrophin mutations resulting in complete loss of dystrophin." (PMID 37534133, 2023). "Duchenne Muscular Dystrophy (DMD) is an X-linked recessive neuromuscular disorder caused by mutations in the DMD gene leading to loss of the dystrophin protein." (PMID 37099511, 2023). "Duchenne muscular dystrophy (DMD) is caused by multiple mutations in the DMD gene, which is located on the X chromosome." (PMID 37101699, 2023). "Duchenne muscular dystrophy and its milder variant Becker muscular dystrophy are both caused by dystrophin gene mutations, which often eliminate 1 or more internal exons or alter proper splicing." (PMID 37909333, 2023). "Duchenne muscular dystrophy (DMD) is an inherited disorder with mutations in the dystrophin gene characterized by progressive muscle degeneration and weakness." (PMID 37950170, 2023). "Duchenne muscular dystrophy (DMD) is a neuromuscular disorder caused by dystrophin loss—notably within muscles and the central neurons system." (PMID 37108685, 2023). "Dystrophin, or the DMD gene, encodes a muscle protein of the same name whose mutant variant is the cause of Duchenne muscular dystrophy." (PMID 36672993, 2023). "Duchenne muscular dystrophy (DMD) is a severe neuromuscular disease that occurs due to mutations in the DMD gene that encodes the subsarcolemmal protein dystrophin." (PMID 37071470, 2023). "Duchenne muscular dystrophy is an X-linked recessive disease caused by mutations in dystrophin proteins that lead to heart failure and respiratory failure." (PMID 36980233, 2023).
Duchenne muscular dystrophy (continued). "Duchenne muscular dystrophy (DMD) is the most common form of muscular dystrophy caused by mutations in the DMD gene on the X chromosome (Xp21.1-Xp22)." (PMID 37501163, 2023). "Approximately 13% of male patients with Duchenne muscular dystrophy carry a nonsense mutation in the DMD gene that expresses a protein called dystrophin." (PMID 37238980, 2023). "Duchenne muscular dystrophy (DMD) is an X-linked recessive genetic disorder characterized by dystrophin (Dys) gene mutations in the dystrophin (Dys) gene that eliminate dystrophin protein expression and destabilize muscle membrane structure." (PMID 37686009, 2023). "Duchenne muscular dystrophy (DMD) is caused by loss of function mutations in the DMD gene that prevent the production of full-length dystrophin." (PMID 36911945, 2023). "Duchenne muscular dystrophy (DMD) is a recessive X-linked hereditary disease caused by mutations in the DMD gene encoding dystrophin protein." (PMID 36768550, 2023). "Duchenne muscular dystrophy (DMD) (OMIM# 310200) is an X-linked recessive inherited disease caused by a mutation in the gene encoding dystrophin (OMIM* 300377)." (PMID 36672993, 2023). "Duchenne Muscular Dystrophy (DMD) is a severe disease caused by genetic variants in the Dystrophin gene." (PMID 37645248, 2023). "Duchenne muscular dystrophy (DMD) is a severe muscle degeneration disorder caused by genomic mutations that result in a frameshift in the dystrophin gene." (PMID 37625413, 2023). "Duchenne muscular dystrophy (DMD) is a muscle disease caused by mutations in the dystrophin gene characterized by myofiber fragility and progressive muscle degeneration." (PMID 37569832, 2023). "Altered mitochondrial structure and function have been observed in induced pluripotent stem cell-derived cardiomyocytes from patients affected by Duchenne muscular dystrophy, an X-linked disease caused by the loss of the dystrophin gene." (PMID 37894956, 2023). "Human patients with Duchenne muscular dystrophy have typically nonsense or frameshift DMD variants with complete loss of dystrophin protein function." (PMID 36834603, 2023). "The molecular signature associated with decreased DMD expression in tumors and corresponding tumor cell lines is concordant with that found in Duchenne muscular dystrophy." (PMID 36900171, 2023). "Duchenne muscular dystrophy (DMD) is caused by pathogenic variants in the DYS1 gene leading to dystrophin loss and the mdx mouse model was developed to study the disease." (PMID 37511627, 2023). "Mutations in the DMD gene, which encodes dystrophin, cause Duchenne muscular dystrophy (DMD) and Becker muscular dystrophy (BMD), one of the most studied forms of MD." (PMID 37176020, 2023). "Duchenne muscular dystrophy is a genetic disease produced by mutations in the dystrophin gene characterized by early onset muscle weakness leading to severe and irreversible disability." (PMID 37673877, 2023). "Impaired muscle regeneration is a hallmark of Duchenne muscular dystrophy (DMD), a neuromuscular disorder caused by mutations in the DMD gene encoding dystrophin." (PMID 36918494, 2023). "Duchenne muscular dystrophy (DMD) is a neuromuscular disease stemming from dystrophin gene mutations." (PMID 37248912, 2023). "Large-scale inversions seem to be a very rare but already identified cause of Duchenne muscular dystrophy: most recently, five inversions affecting the DMD gene were detected using NGS including long-read whole-genome sequencing." (PMID 37834164, 2023). "To address this idea, we employed the Duchenne muscular dystrophy mouse model (mdx), which lacks dystrophin expression due to a nonsense mutation." (PMID 37228645, 2023). "Duchenne muscular dystrophy (DMD) is the most common type of neuromuscular disease caused by mutations in the DMD gene encoding dystrophin protein." (PMID 38203473, 2023). "Functional dystrophin deficiency causes muscle atrophy in people with Duchenne muscular dystrophy (DMD)." (PMID 36531952, 2022).